PLK4 (polo like kinase 4)
Diseases named in the same sentence as PLK4 in open-access papers (continued):
Sharing a sentence is not in itself a finding about the gene and the disease.
lung carcinoma (17 papers, 2009 to 2025). "PLK4 is overexpressed in lung carcinoma and is associated with unfavorable survival; high PLK4 expression correlates with greater tumor size, lymph node metastasis and confers poor survival in non-small cell lung cancer." (PMID 41092110, 2025). "Since PLK4 controls centrosome duplication in human cells, it is considered that PLK4 overexpression caused the centrosome amplification in the lung cancer cells of our system, consistent with the observations in previous studies in cells other than lung cancer cells." (PMID 31137743, 2019). "Furthermore, POLQ overexpression was found to be concurrently associated with Polo Like Kinase 4 (PLK4) overexpression, which was also examined in the lung cancer cell clones." (PMID 31137743, 2019). "Global methylation survival analysis using bioinformatics showed the prognostic value of PLK4 methylation in lung cancer." (PMID 41488365, 2025). "Another study showed that DNA polymerase theta (POLQ) overexpression was positively correlated with PLK4 overexpression in lung adenocarcinoma and induced PLK4-mediated centrosome amplification in lung cancer cells." (PMID 41488365, 2025). "It will be important to study PLK4 in different models of lung cancer to get a better understanding of its precise role." (PMID 41488365, 2025). "Among the 20 cancer types examined in this study, more than half of patients with thyroid cancer, lung cancer, and prostate cancer showed medium to high levels of PLK4 protein expression in IHC staining results using two antibodies (HPA035026, HPA043198)." (PMID 36620611, 2022). "STIL showed the highest T/N ratio (3.5) among the studied genes; this was found in patients with lung cancer, and was even higher than the T/N ratio (1.5) of PLK4 in these patients." (PMID 35365182, 2022). "Plk4 inhibition holds promise in lung cancer therapy either as a single agent or when combined with an agent that deregulates mitosis." (PMID 33777739, 2021). "The present study is the first to show concurrent overexpression of POLQ and PLK4 at both the mRNA and protein level in LAC, and also induction of centrosome amplification in lung cancer cells associated with POLQ and PLK4 overexpression." (PMID 31137743, 2019). "PLK4-/- embryos arrest at stage E7.5 with increased numbers of apoptotic and late mitotic cells, while PLK4+/- embryos develop normally but have an increased incidence of spontaneous liver and lung cancers." (PMID 20920249, 2010). "Plk4-null mice are embryonic lethal and Plk4 heterozygous mice display 15-fold increase in incidence of liver and lung cancers than that of wild type mice." (PMID 19161615, 2009). "PLK4 was also associated with greater tumor size, metastasis, and higher TNM stage in lung cancers." (PMID 41488365, 2025). "PLK4 knockdown in lung cancer cells induced polyploidy and halted cell proliferation." (PMID 41488365, 2025). "Inhibition of PLK4 by CFI-400945 enhances radiosensitivity in lung cancer." (PMID 41092110, 2025). "Compared to normal samples, PLK4 was found to be higher in lung cancer sample." (PMID 34080290, 2021). "Since PLK4 is known to be involved in centrosome regulation, we then investigated whether the number of centrosomes was dysregulated in the lung cancer cells showing concurrent overexpression of POLQ and PLK4." (PMID 31137743, 2019). "For another member of the PLK family, PLK4, was demonstrated that haploinsufficient Plk4 + /- mice have a higher incidence of liver and lung cancer, which was due to an impaired regulation of Cyclins D1, E and B1 and of CDK1 supporting a critical role of polo-like kinases for tissue homeostasis." (PMID 29549256, 2018). "Elderly PLK4+/− mice usually had more chances to develop spontaneous liver and lung cancer." (PMID 22829937, 2012). "However, to date, little is known regarding the role of PLK4 in lung cancer." (PMID 34080290, 2021). "In addition, increased rate of liver and lung cancers was detected in Plk4+/− mice." (PMID 26439168, 2015).
lung carcinoma (continued). "It was found that the inhibition of PLK4 in TFEB and TFE3 double-knockout cells drastically reduced the proliferation of lung cancer cells, providing a rationale for combination therapies." (PMID 41488365, 2025). "Moreover, POLQ overexpression was found to be associated with advanced pathologic stage, increased somatic mutation load, and PLK4 overexpression in lung adenocarcinoma, thus inducing centrosome amplification, indicating the potential involvement of POLQ in the development of lung cancer." (PMID 34517891, 2021). "In the current study, although PLK4 was overexpressed in lung cancer, methylation could not explain the transcriptional and protein expression of PLK4." (PMID 34080290, 2021). "PLK1 expression was higher in male than that in female patients, so was PLK4 expression between genders, whereas PLK2 presented no differential expression between male and female of lung cancer patients." (PMID 34080290, 2021). "Different effects of CFI-400945 and centrinone have already been observed in a lung cancer cell line, leading to the conclusion that CFI-400945′s effects were not solely due to PLK4 inhibition." (PMID 32770382, 2020).
colorectal cancer (16 papers, 2015 to 2025). A primary or metastatic malignant neoplasm that affects the colon or rectum. "PLK4 is commonly mutated in human malignancies in a variety of cancer types, including colorectal cancer." (PMID 40136426, 2025). "In colorectal cancer, tumors with mutant PLK4 typically have a higher tumor mutational burden and are usually associated with advanced tumor progression stages." (PMID 40136426, 2025). "Tumors bearing mutant PLK4 tend to have higher tumor mutational burden and are usually associated with advanced stages of tumor progression in colorectal cancer." (PMID 38951519, 2024). "To investigate the importance of centrosomes in colorectal cancer, we induced centrosome loss in normal and cancer human-derived colorectal organoids using centrinone B, a Polo-like kinase 4 (Plk4) inhibitor." (PMID 38324534, 2024). "In human tumors, PLK4 is frequently mutated in many types of cancer, including colorectal cancer." (PMID 38951519, 2024). "For example, Liao and colleagues have shown that PLK4 knockdown inhibited the Wnt/β-catenin pathway in colorectal cancer cells both in vitro and in vivo, leading to reduced xenografted tumor growth in nude mice." (PMID 40940791, 2025). "PLK4 overexpression upregulated epithelial-to-mesenchymal transition (EMT) markers in polyploid giant cancer cells, which declined upon PLK4 knockout in colorectal cancer." (PMID 41488365, 2025). "In colorectal cancer, high PLK4 expression promotes EMT and tumor progression via regulation of the Wnt/β-catenin pathway." (PMID 41092110, 2025). "Inhibition of PLK4 by CFI-400945 leads to overcoming oxaliplatin resistance in colorectal cancer mouse xenograft models." (PMID 41092110, 2025). "As an example, we validated PLK4 as an actionable target against oxaliplatin resistance in colorectal cancer and explored the potential of using PLK4 inhibitor CFI-400945 to treat oxaliplatin-resistant tumors." (PMID 38951519, 2024). "High expression of PLK4 is an independent factor predicting poor OS in patients with colorectal cancer." (PMID 38326803, 2024). "To test the validity of convergent targeting strategy, we preferentially focused on the top hit PLK4 for its roles and targeting potential against oxaliplatin resistance in colorectal cancer." (PMID 38951519, 2024). "Such vulnerability creates an opportunity to apply single-agent PLK4-targeting drug for the treatment of oxaliplatin-resistant colorectal cancers." (PMID 38951519, 2024). "It has been reported that PLK4 is highly expressed in several tumor types, such as breast, colorectal cancers, glioblastoma, and bladder cancer." (PMID 29352113, 2018). "Transcript levels of Plk4 in the breast, floor of mouth, lymphatic and colorectal cancers are clearly upregulated (redundant probe sets yield similar fold changes and significances)." (PMID 26439168, 2015). "PLK4 overexpression was associated with increased tumor, nodes, and metastasis (TNM) stage and shorter disease-free survival in stomach adenocarcinoma and colorectal cancer patients." (PMID 41488365, 2025). "Collectively, these data suggest that single-agent administration with PLK4 inhibitor CFI-400945 may be a promising therapeutic strategy to overcome oxaliplatin-involved chemoresistance in colorectal cancer." (PMID 38951519, 2024). "On the other hand, Plk4 also promotes EMT via Wnt/β-catenin in colorectal cancer." (PMID 36797240, 2023). "As noted in previous colorectal cancer patient cohorts, Plk4 was increased in T vs. matched NM." (PMID 32807875, 2020). "Similarly, and in agreement with previous studies in colorectal cancer, the Plk4 expression was also significantly higher in B-ALL patients compared to normal cells." (PMID 32060361, 2020).
colorectal cancer (continued). "Additionally, we discuss potential mechanistic insights into PLK4′s involvement in skin cancer progression by extrapolating evidence from studies in other cancer types including colorectal cancer, thyroid cancer, lymphomas, leukemia, etc., while identifying gaps for future research." (PMID 40940791, 2025). "In addition, PLK4 has been identified as an oncogene, which is overexpressed in various types of human cancers, and functional studies revealed that knockdown of PLK4 in colorectal cancer cells results in a significant decrease in cell viability and proliferation." (PMID 38935637, 2025). "We also show for the first time that unlike other centriolar Plk4 interactors, FAM46C is depleted in human colorectal cancer tumor tissue, compared with paired normal mucosa samples taken from the same patient." (PMID 32807875, 2020).
glioblastoma (13 papers, 2018 to 2025). The most malignant astrocytic tumor (WHO grade IV). "Downregulation of PLK4 expression in glioblastoma cell lines or its inhibition in intracranial tumor mouse models leads to alterations in chemokines’ expression and promotes recruitment of tumor infiltrating M1 macrophages." (PMID 41092110, 2025). "PLK4 mRNA and protein are overexpressed in glioblastoma; PLK4 promotes proliferation and tumorigenesis; increased PLK4 expression is associated with poor prognosis; PLK knockdown increases radiosensitivity and sensitivity to temozolomide and bortezomib." (PMID 41092110, 2025). "Further PLK4 promotes vasculogenic mimicry (VM), a process where aggressive glioblastoma (GBM) cells form vessel-like structures contributing to resistance against anti-angiogenic therapies." (PMID 40940791, 2025). "ATAD2, an ATPase domain-containing protein, is also known to upregulate PLK4 transcription, which was demonstrated in glioblastoma (GB) cells." (PMID 41488365, 2025). "Based on TGGA and CGGA datasets, we then examined the relationship between PLK4 expression levels and prognosis of patients with oligodendrogliomas, astrocytomas, and glioblastomas." (PMID 36620611, 2022). "The survival rate of glioblastoma patients in PLK4-high groups was worse than that of patients in PLK4-low groups in the CGGA_693 and CGGA_325 datasets." (PMID 36620611, 2022). "Knockdown of PLK4 leads to the radiosensitivity of various cancers, such as glioblastoma." (PMID 41092110, 2025). "PLK4 overexpression was shown to be correlated with poor prognosis in glioblastoma patients." (PMID 41488365, 2025). "PLK4 promoted cell proliferation and tumorigenesis of glioblastoma." (PMID 34080290, 2021). "Therefore, PLK4 may serve as a valuable prognostic biomarker in the treatment of glioblastoma and other types of cancer." (PMID 36620611, 2022). "This PLK4-NF-κB interaction has also been studied in glioblastoma where PLK4 was found to induce NF-κB transactivation and increased chemoresistance by phosphorylating IKK-epsilon (IKBKE) in glioblastoma cells." (PMID 40940791, 2025). "Exogenous ATAD2 overexpression can significantly increase the expression of Polo-like kinase 4 (PLK4) to promote the occurrence and radiation resistance of glioblastoma (GBM), and so ATAD2 may be a key regulator of PLK4 transcription in GBM." (PMID 36008934, 2022).
melanoma (13 papers, 2018 to 2025). A malignant, usually aggressive tumor composed of atypical, neoplastic melanocytes. "Additionally, Plk4 overexpression was associated with centriole overduplication in tissue microarray of human melanomas, which means that the expression of Plk4 is the main driver of melanoma centriole duplication." (PMID 33777739, 2021). "PLK4 was found to be significantly overexpressed in melanoma tissues as compared to benign tissue, which correlated with poor patient survival." (PMID 41488365, 2025). "It was also validated in a panel of human melanoma cell lines, where PLK4 overexpression was correlated with centriole overduplication, and its inhibition by a centrinone B resulted in depleted centrioles and reduced proliferation of melanoma cells." (PMID 41488365, 2025). "For example, TENT5C was identified as a tumor suppressor, exerting its function by inhibiting Plk4 activity in melanoma." (PMID 38502270, 2024). "First, we overexpressed HER2 in noninvasive melanoma cells to mimic the condition in the SK-Mel-173 cells upon PLK4 overexpression and found a clear induction in MT growth rates as seen in invasive melanoma cells." (PMID 36875714, 2022). "Other inhibitors target the critical role of PLK4 in centriolar function and inhibit cell proliferation in melanoma cells, breast cancer, cervical carcinoma, and colon carcinoma only to name a few." (PMID 34065956, 2021). "Further investigation demonstrated that centrinone B, a selective Plk4 inhibitor, depleted centrioles and induced apoptosis in A375 and Hs294T melanoma cells, suggesting Plk4 is a potential biomarker and drug target in melanoma." (PMID 33777739, 2021). "Although PLK4 has been found to be overexpressed in a number of adult peripheral tumors like colorectal, breast, lung, melanoma, leukemia, and pancreatic cancer, we were the first to report PLK4 overexpression in embryonal tumors and in pediatric brain tumors." (PMID 30400339, 2018). "PLK4 overexpression has been observed in multiple cancers, including melanoma and non-melanoma skin cancers and is often associated with poor clinical outcomes." (PMID 40940791, 2025). "While elevated PLK4 levels do not always correlate with centrosome amplification, pharmacological inhibition of PLK4 using centrinone B was shown to suppress proliferation and induced apoptosis in melanoma cells, highlighting PLK4 as a viable therapeutic target for melanoma management." (PMID 40940791, 2025). "PLK4 is overexpressed in melanoma samples and human melanoma cell lines; elevated expression of PLK4 correlates with aggressive tumor characteristics, lymph node metastases, and shortened DFS and OS in patients with cutaneous melanoma who underwent surgical resection." (PMID 41092110, 2025). "Additionally, PLK4 was also found to be significantly overexpressed in melanoma tissues and cell lines compared to normal samples." (PMID 40940791, 2025). "However, upon data filtering and imputation we identified 172 proteins that were significantly enriched at least 1.5-fold in MVs derived from PLK4-overexpressing melanoma cells." (PMID 36875714, 2022). "Compared with normal melanocytes, Plk4 was found to be dramatically upregulated in melanoma." (PMID 33777739, 2021). "Although multivariate analysis did not identify PLK4 as an independent prognostic factor, RNA expression data from the Human Protein Atlas confirmed that high PLK4 levels were associated with shorter overall survival in melanoma patients." (PMID 40940791, 2025). "Thus it appears unlikely that the effect of FAM46C on Plk4-dependent centriole duplication is related to its RNA polymerase function, at least in the cancer cell types we have studied here, which include osteosarcoma, melanoma and colorectal adenocarcinoma." (PMID 32807875, 2020). "This presented PLK4 as a crucial promoter of melanoma and NMSC progression, which requires further in-depth exploration using different in vitro and in vivo melanoma models." (PMID 41488365, 2025).
melanoma (continued). "We verified HER2 enrichment in MVs derived from noninvasive melanoma cells upon PLK4 overexpression by Western blotting while the cellular levels of HER2 were not changed indicating that PLK4 overexpression might cause enrichment of HER2 in MVs, but does not affect HER2 expression." (PMID 36875714, 2022). "We first reflect on the current knowledge of PLK4′s involvement in melanoma, non-melanoma skin cancer, and other dermatologic conditions." (PMID 40940791, 2025). "The higher the Plk4 expression level was, the worse the survival rate was, but the difference was not significant in the TCGA melanoma dataset." (PMID 33777739, 2021). "To this end, we induced centrosome amplification by overexpression of key regulators involved in the centrosome duplication cycle, namely, PLK4 and STIL, in noninvasive melanoma cells that show otherwise no aberrant centrosome numbers." (PMID 36875714, 2022).